ACSM1 (acyl-CoA synthetase medium chain family member 1)
Description:
Catalyzes the activation of fatty acids by CoA to produce an acyl-CoA, the first step in fatty acid metabolism. Capable of activating medium-chain fatty acids (e.g. butyric (C4) to decanoic (C10) acids), and certain carboxylate-containing xenobiotics, e.g. benzoate. Also catalyzes the activation of lipoate to lipoyl-nucleoside monophosphate (By similarity). Activates lipoate with GTP at a 1000-fold higher rate than with ATP and activates both (R)- and (S)-lipoate to the respective lipoyl-GMP, with a preference for (R)-lipoate (By similarity).
Synonyms: BUCS1; MACS1
Tractability: No criterion of Open Targets' tractability assessment is met for any kind of drug.
Gene: Protein-coding gene on chromosome 16 (20,623,233 to 20,698,890, reverse strand). Ensembl gene ENSG00000166743.
Subcellular location: Mitochondrion matrix; Mitochondrion
Pathways (Reactome):
Metabolism: Conjugation of benzoate with glycine; Conjugation of phenylacetate with glutamine
Gene Ontology:
Molecular function: benzoate-CoA ligase activity; decanoate-CoA ligase activity; long-chain fatty acid-CoA ligase activity; medium-chain fatty acid-CoA ligase activity; protein binding; CoA-ligase activity; fatty acid ligase activity; fatty-acyl-CoA synthase activity; short-chain fatty acid-CoA ligase activity
Biological process: acyl-CoA metabolic process; benzoate metabolic process; butyrate metabolic process; cholesterol homeostasis; energy derivation by oxidation of organic compounds; fatty acid biosynthetic process; fatty acid oxidation; xenobiotic metabolic process; long-chain fatty acid metabolic process
Cellular component: blood microparticle; extracellular exosome; mitochondrial matrix; mitochondrion
Genetic constraint (gnomAD): Loss-of-function variants: 74 observed, 71.94 expected, observed/expected ratio (o/e) 1.03, 90% interval 0.85 to 1.25. The upper end of that interval is the gene's LOEUF score, 1.25, which puts it in group 5 of 6, group 1 being the genes least tolerant of losing a copy. Missense variants: 628 observed, 692.09 expected, observed/expected ratio (o/e) 0.91, 90% interval 0.85 to 0.97. Synonymous variants: 259 observed, 259.38 expected, observed/expected ratio (o/e) 1, 90% interval 0.9 to 1.11.
Homologues: Orthologues: macaque ACSM1 (90% identical), chimpanzee ACSM1 (83% identical), mouse Acsm1 (70% identical), rabbit ACSM1 (66% identical), rat Acsm1 (66% identical), guinea pig ACSM1 (60% identical), tropical clawed frog acss2.2 (26% identical), zebrafish acss2l (25% identical), Caenorhabditis elegans acs-1 (18% identical), Caenorhabditis elegans acs-2 (17% identical). Paralogues in human: ACSM2A (55% identical), ACSM2B (55% identical), ACSM5 (55% identical), ACSM4 (55% identical), ACSM3 (52% identical), ACSM6 (35% identical), ACSS2 (28% identical), ACSS1 (27% identical), ACSS3 (25% identical), ACSF2 (21% identical), ACSF3 (19% identical), AACS (18% identical), and 1 more.
Diseases named in the same sentence as ACSM1 in open-access papers:
ACSM1 is named in the same sentence as 20 diseases in open-access papers, as found by Europe PMC text mining. Sharing a sentence is not in itself a finding about the gene and the disease. The quoted sentences say what the papers report.
breast carcinoma (3 papers, 2013 to 2024). "ACSM1 has not been previously associated with PCa progression, but was reported as a potential marker for the invasive apocrine subtype of breast cancer, a rare subtype that is associated with AR+ status and poor differentiation." (PMID 27196083, 2016).
apocrine carcinoma (2 papers, 2013 to 2023). "However, apocrine carcinoma-associated genes such as ACSM1, FABP7, and HMGCS244 showed significant upregulation in TNAC compared to LK-TNBC (Wilcoxon signed-rank test, p < 0.05)." (PMID 37394589, 2023). "Clusters of differentially correlated genes could be interpreted biologically and included the marker genes hydroxyprostaglandin dehydrogenase (PGDH) and acyl-CoA synthetase medium chain 1 (ACSM1) of invasive apocrine carcinomas that were differentially correlated, but not differentially expressed." (PMID 23945349, 2013).
prostate carcinoma (2 papers, 2024). A carcinoma that arises from epithelial cells of the prostate gland. "ACSM1 is highly expressed in prostate cancer and promotes its metastasis through the extracellular matrix-receptor interaction signaling pathway." (PMID 39478854, 2024).
apocrine carcinoma of the breast (1 paper, 2023). "ACSM1 is usually used as a molecular marker of apocrine carcinoma of the breast." (PMID 37426827, 2023).
Hypertension (1 paper, 2021). The presence of chronic increased pressure in the systemic arterial system. "Interestingly, Acsm3 was previously identified as a candidate gene for hypertension and other MetS traits as part of the SAH (spontaneously hypertensive rat-clone A-hypertension associated, together with Acsm2 and Acsm1), but the association with hypertension was not confirmed." (PMID 33923085, 2021).
nicotine dependence (1 paper, 2017). Physical and psychological dependence on nicotine. "SNPs annotated to genes previously associated to obesity traits (LINGO2, NELL1) and neurological disorders (schizophrenia (ACSM1, KIF26B, NALCN)), and alcohol and nicotine dependence (LINGO, SH3BP5) were found among Prudent reported dietary pattern score associated-SNPs." (PMID 28644415, 2017).
ovarian carcinoma (1 paper, 2024). A malignant neoplasm originating from the surface ovarian epithelium. "In the present study, RPL23, FGFR1OP2, CAPN10, ALDH1L1 and ACSM1 were significantly downregulated in ovarian cancer, while the up-regulation of RPL23, FGFR1OP2, CAPN10 and ALDH1L1 was associated with poor prognosis in patients with ovarian cancer." (PMID 39478854, 2024). "PKM2, MRPS12, NDUFC2, HPDL, MRPL14, COA6 and RNF144B were significantly upregulated in ovarian cancer tissues than in normal tissues (P < 0.05), while RPL23, FGFR1OP2, CAPN10, ALDH1L1 and ACSM1 were significantly down-regulated (P < 0.05)." (PMID 39478854, 2024).
steatosis (1 paper, 2018). Increased lipid within the cytoplasm of cells. "The presence of ACSM1 in non-treated rats indicated high deposition of triglycerides in hepatocytes and led to higher severity of steatosis than that in sericin-treated rats." (PMID 30297713, 2018).
thyroid cancer (1 paper, 2023). "ACSM1 and ACSM5 have been reported to be associated with the progression of prostate and thyroid cancers, respectively." (PMID 37426827, 2023).
tumor (3 papers, 2016 to 2024). "In addition, silencing of PLA2G7, RHOU, ACSM1, LAMB1 and CACNA1D also resulted in reduced tumor cell invasion in PC3 organoid cultures." (PMID 27196083, 2016).
ACSM1 also shares sentences with these, for which no sentence is quoted: cancer (2 papers); infection (2); bladder cancer (1); colon cancer (1); lung agenesis (1); melanoma (1); neurological disorders (1); Obesity (1); pituitary tumor (1); schizophrenia (1).